INA (internexin neuronal intermediate filament protein alpha)
Description:
Class-IV neuronal intermediate filament that is able to self-assemble. It is involved in the morphogenesis of neurons. It may form an independent structural network without the involvement of other neurofilaments or it may cooperate with NEFL to form the filamentous backbone to which NEFM and NEFH attach to form the cross-bridges. May also cooperate with the neuronal intermediate filament protein PRPH to form filamentous networks (By similarity).
Synonyms: NF-66; NEF5; NF66; TXBP-1
Tractability: PROTAC: ubiquitination databases record sites on it; its protein half-life has been measured.
Gene: Protein-coding gene on chromosome 10 (103,277,138 to 103,290,351, forward strand). Ensembl gene ENSG00000148798.
Subcellular location (Human Protein Atlas): Intermediate filaments; Cytosol
Gene Ontology:
Molecular function: protein binding; structural constituent of cytoskeleton; structural constituent of postsynaptic intermediate filament cytoskeleton
Biological process: substantia nigra development; intermediate filament organization; postsynaptic intermediate filament cytoskeleton organization; postsynaptic modulation of chemical synaptic transmission
Cellular component: cytoplasmic ribonucleoprotein granule; extracellular region; intermediate filament; neurofilament; postsynaptic intermediate filament cytoskeleton; intermediate filament cytoskeleton; postsynapse; Schaffer collateral - CA1 synapse
Genetic constraint (gnomAD): Loss-of-function variants: 33 observed, 29.78 expected, observed/expected ratio (o/e) 1.11, 90% interval 0.84 to 1.48. The upper end of that interval is the gene's LOEUF score, 1.48, which puts it in group 6 of 6, group 1 being the genes least tolerant of losing a copy. Missense variants: 583 observed, 607.59 expected, observed/expected ratio (o/e) 0.96, 90% interval 0.9 to 1.03. Synonymous variants: 288 observed, 276.45 expected, observed/expected ratio (o/e) 1.04, 90% interval 0.94 to 1.15.
Homologues: Orthologues: chimpanzee INA (99% identical), macaque INA (99% identical), rabbit INA (97% identical), dog INA (97% identical), pig INA (97% identical), rat Ina (95% identical), guinea pig INA (95% identical), mouse Ina (94% identical), tropical clawed frog ina (62% identical), zebrafish inaa (56% identical), zebrafish inab (56% identical). Paralogues in human: NEFM (48% identical), NEFL (46% identical), PRPH (43% identical), VIM (43% identical), DES (41% identical), GFAP (37% identical), KRT75 (29% identical), KRT73 (28% identical), KRT71 (28% identical), KRT8 (28% identical), KRT5 (27% identical), KRT74 (27% identical), and 56 more.